HOXD13 (homeobox D13)
Diseases named in the same sentence as HOXD13 in open-access papers (continued):
Sharing a sentence is not in itself a finding about the gene and the disease.
colon cancer (6 papers, 2018 to 2025). "HOXD13 has been implicated in various cancers, including colon cancer, where its knockdown inhibits cell proliferation and invasion." (PMID 39744569, 2025). "For example, the upregulated HOXC10 promotes ESCC proliferation both in vitro and in vivo, HOXD13 has been reported to promote the malignant progression of colon cancer." (PMID 37393256, 2023). "Our experimental results show that HOXD13 is highly expressed in colon cancer and is positively correlated with colon cancer metastasis." (PMID 34272834, 2021). "The Cancer Genome Atlas database was used to analyze the expression of HOXD13 and its effect on the survival rate of colon cancer patients." (PMID 34272834, 2021). "The knockdown of HOXD13 can significantly inhibit the proliferation, migration, and invasion of colon cancer cells." (PMID 34272834, 2021). "In in vitro experiments, the knockdown of HOXD13 can inhibit the proliferation and invasion of colon cancer cells." (PMID 34272834, 2021). "Both in vitro and in vivo experiments have shown HOXD13's cancer‐promoting function in colon cancer cells." (PMID 34272834, 2021). "The expression of HOXD13 in metastatic (M1) colon cancer is also higher than that in the non‐metastatic (M0) type." (PMID 34272834, 2021). "Wound healing, Transwell, and clone formation were used to evaluate the effects of changes in HOXD13 expression on the function of colon cancer cells." (PMID 34272834, 2021). "In vitro experiments have shown that HOXD13 can promote colon cancer cell migration, invasion, and clonal formation." (PMID 34272834, 2021). "After detecting the expression of HOXD13 in six colon cancer cell lines by Western blot, we selected LoVo cells with the highest expression of HOXD13 and CW‐2 cells with the lowest expression." (PMID 34272834, 2021). "Our results showed that HOXD13 was highly expressed in colon cancer and predicted a poor prognosis for patients." (PMID 34272834, 2021). "Next, we used IHC and Western blot to detect the expression of HOXD13 in clinical samples, and both showed the high expression of HOXD13 in colon cancer." (PMID 34272834, 2021). "The function of transcription factor HOXD13 in colon cancer is likely to be exerted by its regulated genes." (PMID 34272834, 2021). "We conducted a rescue experiment to further confirm whether PTPRN2 mediates the tumor‐promoting effect of HOXD13 in colon cancer." (PMID 34272834, 2021). "The promotion of HOXD13 in colon cancer is partly achieved by PTPRN2." (PMID 34272834, 2021). "We revealed the function and mechanism of HOXD13 in colon cancer and suggest that HOXD13 may be a candidate marker for the diagnosis and treatment of colon cancer." (PMID 34272834, 2021). "HOXD13 is highly expressed in colon cancer patients and indicates a poor prognosis." (PMID 34272834, 2021). "Our study illustrates the positive regulatory role of HOXD13 in colon cancer." (PMID 34272834, 2021). "Overall, HOXD13 promotes the malignant progression of colon cancer through PTPRN2." (PMID 34272834, 2021). "In addition, HOXD13 expression is high in patients with colon cancer and predicts a poor prognosis." (PMID 34272834, 2021). "Cell and animal experiments show that HOXD13 can bind to PTPRN2 (Protein tyrosine phosphatase, receptor type N2) promoter and up-regulate its expression, thus promoting the development of colon cancer." (PMID 38336605, 2024). "This research also explains the transcriptional regulatory relationship between HOXD13 and protein tyrosine phosphatase receptor type N2 (PTPRN2) and their mechanisms in the malignant progression of colon cancer." (PMID 34272834, 2021). "However, the function of HOXD13 in colon cancer remains unclear." (PMID 34272834, 2021). "We have recently shown their de-regulation in colon cancer, describing the absence of expression of HOXA13, HOXB13, HOXC13 and HOXD13 in the normal colon mucosa, a slight increase in expression in the transitional mucosa, up to in many cases over-expressed in the tumor." (PMID 34208964, 2021).
Ewing sarcoma (6 papers, 2017 to 2024). A small round cell tumor that lacks morphologic, immunohistochemical, and electron microscopic evidence of neuroectodermal differentiation. "Significantly, high expression of posterior HOXD genes, especially HOXD13, is a hallmark of Ewing sarcoma." (PMID 30845695, 2019). "The research of ewing sarcoma exhibited that HOXD11 and HOXD13 promoted growth and metastasis of ewing sarcoma." (PMID 32557953, 2020). "We recently reported that high expression of posterior Homeobox D gene cluster (HOXD) genes is a hallmark of Ewing sarcoma and that ectopic expression of EWS-FLI1 in neural crest-derived MSCs hijacks normal epigenetic regulation of HOXD10, HOXD11, and HOXD13." (PMID 30845695, 2019). "Human Ewing sarcoma tumors over-express HOXD10, HOXD11, and HOXD13 and maintenance of the tumorigenic Ewing sarcoma state requires continued high-level expression of HOXD13." (PMID 30845695, 2019). "HOXD10, HOXD11 and HOXD13 play essential roles in maintaining the oncogenic phenotype of Ewing sarcoma proliferation, invasion and metastasis (current study and Ref." (PMID 27888797, 2017). "Posterior HOXD genes are abnormally over-expressed by Ewing sarcoma and HOXD13, in particular, contributes to the tumorigenic phenotype." (PMID 27888797, 2017). "Furthermore, our studies utilizing a Hoxd13 null mouse model have facilitated a more complete understanding of the molecular mechanisms of murine Ewing sarcoma." (PMID 30845695, 2019). "While posterior HOXD genes (from HOXD13 to HOXD9) promote chondrogenic differentiation and enhance bone-associated gene expression, HOXD11 and HOXD13 are specifically involved in cell growth and invasion of Ewing sarcoma." (PMID 31137568, 2019). "We and others have shown that the posterior HOXD genes, HOXD9, HOXD10, HOXD11, and HOXD13 are overexpressed by Ewing sarcoma and that the promoters of these genes are devoid of the repressive H3K27me3 mark and highly enriched with the MLL-mediated H3K4me3 mark." (PMID 27888797, 2017). "Nevertheless, given that MLL1 directly activates HOX genes in embryonic development, our data lend strong support for the hypothesis that MLL1 also contributes to epigenetic activation of HOXD13 in Ewing sarcoma." (PMID 27888797, 2017). "In addition, knockdown of HOXD13, and also of HOXD10 and HOXD11, results in loss of tumorigenicity, verifying the identity of posterior HOXD genes as critical oncogenes in Ewing sarcoma." (PMID 27888797, 2017). "Notably, posterior HOXD genes, particularly HOXD13, are markedly overexpressed by Ewing sarcoma cells and the promoters of these genes are enriched with the TrxG-dependent H3K4me3 histone modification, consistent with a transcriptionally active chromatin state." (PMID 27888797, 2017). "Menin knockdown in multiple Ewing sarcoma cell lines also reduces the expression of HOXD13 and HOXD10, both of which are frequently overexpressed in Ewing sarcomas." (PMID 39336822, 2024). "This suggests that Hoxd13, while critical for human Ewing sarcoma tumorigenicity, is not required in mouse EWS-FLI1 induced transformation." (PMID 30845695, 2019). "In the context of human Ewing sarcoma, knockdown of HOXD10, HOXD11, and HOXD13 all independently impaired the growth and invasive properties of tumor cells, demonstrating that despite the marked over-expression of HOXD13, all members of the posterior HOXD cluster contribute to human tumorigenesis." (PMID 30845695, 2019).
gastric cancer (6 papers, 2021 to 2025). A primary or metastatic malignant neoplasm involving the stomach. "Besides, it could also promote gastric cancer cell metastasis ability and reduce the sensitivity to 5-fluorouracil by regulating Homeobox D13." (PMID 34350290, 2021). "In gastric cancer, GALNT10 interacts with HOXD13, modulating cell proliferation and migration." (PMID 39744569, 2025).
brachydactyly (5 papers, 2008 to 2025). A disease characterized by the presence of brachydactyly, including syndromic and non-syndromic forms. "Other heterozygous mutations of HOXD13 cause isolated brachydactyly such as brachydactyly type E (OMIM113300), and the reason for this is unclear." (PMID 32509852, 2020). "Variations in HoxD13 mutations have been identified to cause overlapping conditions such as brachydactyly, syndactyly, and brachydactyly–syndactyly syndrome, among others, and therefore the term “HoxD13 limb morphopaties” has been adopted to encompass all HoxD13-related malformations." (PMID 33567785, 2021). "Hence, the degree of brachydactyly associated with a defective HOXD13 protein is expected to be less pronounced in the preaxial digit because of an undisturbed HOXA13." (PMID 32509852, 2020). "HOXD13 mutations result in a spectrum of limb disorders including brachydactyly." (PMID 18554391, 2008). "Mutations in HOXD13, critical for autopod patterning and elongation, lead to types A4, D, and E. The severity of brachydactyly correlates with the degree of HOXD13 expression, as lower expression levels yield shorter bones." (PMID 41036481, 2025).
synpolydactyly type 1 (4 papers, 2014 to 2022). Any non-syndromic synpolydactyly in which the cause of the disease is a mutation in the HOXD13 gene. "Through genetic research involving several SD families, it was found that syndactyly type I-c, SPD1 (synpolydactyly type 1) and syndactyly type V (SDTY5; MIM# 186,300) were caused by mutations in homeobox D13 (HOXD13) and the c." (PMID 36195906, 2022).
clubfoot (3 papers, 2023 to 2024). The most common congenital deformation of the foot, occurring in 1 of 1,000 live births. "For example, a polyalanine expansion in the N-terminus of the HOXD13 gene results in polydactyly in humans, and idiopathic congenital clubfoot is associated with mutations in the HOXD12 and HOXD13." (PMID 38308324, 2024). "HOXD12 and HOXD13 single nucleotide polymorphisms (SNPs) have been associated with idiopathic clubfoot." (PMID 37964341, 2023). "Initially, genes associatedwith clubfoot (PITX1, TBX4, HOXA9, HOXD10, HOXD12,HOXD13, HOXA9, TPM1, TPM2, COL9A1, FLNB, CASP8,CASP10, UTX, CHD1, RIPPLY2, CAND2, WNT7) werescreened for potential variants." (PMID 38952703, 2024).
endometrial cancer (3 papers, 2013 to 2025). Primary or metastatic malignant neoplasm involving the endometrium (mucous membrane that lines the endometrial cavity). "All EpiMods demonstrated strong enrichment for biological terms, with the HAND2 EpiMod itself highly enriched for other transcription factors (e.g., GATA4, HEY2, HOXD13, PHOX2A, HAND1), all of which were also hypermethylated in endometrial cancer." (PMID 24265601, 2013).
benign breast disease (2 papers, 2016 to 2018). "However, the unmethylation frequency of HOXD13 is significantly increased in the sera from healthy women (97.55%) and patient group with benign breast diseases (99.58%)." (PMID 26918343, 2016).
cervical cancer (2 papers, 2023 to 2025). A primary or metastatic malignant neoplasm involving the cervix. "The aim of this first study in the Mexican population was to search for and analyze variants in the coding region of the HOXC13 and HOXD13 genes in women with cervical cancer." (PMID 36833285, 2023). "To date, the analysis of the HOXC13 and HOXD13 genes in cervical cancer is limited to expression studies; thus, the results generated in this initial research work have contributed new information in the hope of enriching the molecular basis of the disease." (PMID 36833285, 2023).
lung squamous cell carcinoma (2 papers, 2022 to 2025). "Conversely, in several cancers—including GBM, head and neck squamous cell carcinoma (HNSC), lung squamous cell carcinoma (LUSC), skin cutaneous melanoma (SKCM), and UCS—HOXD13 was highly expressed in tumors but exhibited low or absent expression in the corresponding normal tissues." (PMID 39977830, 2025).
lymph node metastasis (2 papers, 2017 to 2022). "High FIGO stage also highly correlated with high HOXB7 expression, and lymph node metastasis was found to be associated with high HOXD12 and HOXD13 expression (P < 0.01)." (PMID 29137433, 2017).
osteosarcoma (2 papers, 2016 to 2025). A usually aggressive malignant bone-forming mesenchymal neoplasm, predominantly affecting adolescents and young adults. "Furthermore, qRT-PCR confirmed a significantly lower expression of HOXD10, HOXD11 and HOXD13 in neuroblastoma and osteosarcoma." (PMID 27363011, 2016).
polydactyly (2 papers, 2024 to 2025). A disease characterized by the presence of polydactyly, including syndromic and non-syndromic forms. "Various exome sequencing and targeted gene studies have implicated several genes in congenital limb defects, including polydactyly (e.g., GLI3, TWIST1, HOXD13, etc.), syndactyly (FGFR2, GLI3, HOXD13, GJA1, etc.), and ectrodactyly, e.g., TP6315,24." (PMID 41510282, 2025).
breast adenocarcinoma (1 paper, 2023). "On one hand, the analysis indicated that both HOXC13 and HOXD13 can be held as mutational cancer drivers in breast adenocarcinomas and esophageal tumors, respectively, highlighting their proliferation-inducing capacity." (PMID 36833285, 2023).
cleft palate (1 paper, 2021). Cleft palate is a fissure type embryopathy that affects the soft and hard palate to varying degrees. "This comprehensive analysis revealed decreases in gene expressions associated with lung development; Foxa2, Notch1, Foxp2, Nkx2.1, and intestine development; Cdx2, Foxf2, Foxl1, and skeletal development; Hoxd12, Hoxd13, Scx, Brachyury, and cleft palate; Foxf2." (PMID 34671097, 2021).
cystic teratoma (1 paper, 2024). "The most interesting findings of this study are amplifications of EVX2, HOXD13, HOXD12, HOXD11, HOXD10, and HOXD9 on a 41.6 kb segment of 2q31.1 in all nine mature cystic teratomas." (PMID 38907278, 2024). "In summary, amplifications of EVX2, HOXD13, HOXD12, HOXD11, HOXD10, and HOXD9 on 2q31.1, NDUFV1 on 11q13.2, and RPL10, SNORA70, DNASE1L1, TAZ, ATP6AP1, and GDI1 on Xq28 were found in all nine mature cystic teratomas in this study." (PMID 38907278, 2024).
Epiphyseal dysplasia (1 paper, 2018). "Furthermore, our findings suggest that p.G11A of HOXD13 may cause severe short stature without limb deformity, and that the p.D401N variant of the COMP gene may cause multiple epiphyseal dysplasia." (PMID 30541462, 2018).
holoprosencephaly (1 paper, 2016). Holoprosencephaly (HPE) is a complex brain malformation resulting from incomplete cleavage of the prosencephalon, occurring between the 18th and 28th day of gestation, and affecting both the forebrain and face, which results in neurological manifestations and facial anomalies of variable severity. "However, only mutations of HOXD13 and FOXF1 have been reported in humans with VACTERL association, while SHH and GLI2 mutations are associated with holoprosencephaly." (PMID 28003020, 2016).
Infertility (1 paper, 2024). "Other etiological possibilities are a diabetic mother, a baby born out of infertility treatment, and exposure to lead, anticonvulsants, estrogen or progesterone-containing compounds, or alcohol during the period of embryogenesis causing mutations in the genes like HOXD13, FOXF1, and ZIC3." (PMID 39463584, 2024).
neuroblastoma (1 paper, 2016). Neuroblastoma (NB) is the most common solid, extracranial childhood tumor. "Interestingly, only HOXD10, HOXD11 and HOXD13 of the homeobox loci, normally involved in bone formation and ossification pattern of bones, were significantly up-regulated in ES in comparison to neuroblastoma, normal and fetal tissue." (PMID 27363011, 2016).
omphalocele (1 paper, 2018). Omphalocele is an embryopathy classified in the group of abdominal celosomias and is characterized by a large hernia of the abdominal wall, centered on the umbilical cord, in which the protruding viscera are protected by a sac. "In our study, significantly lowered expression of HOXD13 in TiO2 NPs treated embryos corroborate with the observed omphalocele." (PMID 29555972, 2018).
prostate tumors (1 paper, 2011). "Several transcription factors, including NKX3-1, HOXB13, HOXC6, HOXD11 and HOXD13, were also found to have deregulated expression in the stromal reaction to invasive prostate tumors." (PMID 21611158, 2011).
renal agenesis (1 paper, 2021). Renal agenesis (RA) is a form of renal tract malformation characterized by the complete absence of development of one or both kidneys (unilateral RA or bilateral RA respectively), accompanied by absent ureter(s). "Moreover, in our study, ectopic PRKX overexpression seemed to upregulate HOXD13, whose alteration has been linked to syndromes affecting genitourinary development, renal agenesis, and limb malformations such as synpolydactyly and polydactyly." (PMID 34063745, 2021).
teratoma (1 paper, 2024). A non-seminomatous germ cell tumor characterized by the presence of various tissues which correspond to the different germinal layers (endoderm, mesoderm, and ectoderm). "In this study, HODX9 (which affects cartilage formation) to HOXD13 (which affects the ossification of mature bone) were amplified in all our teratoma samples." (PMID 38907278, 2024).